PUS7 (pseudouridine synthase 7)
Diseases named in the same sentence as PUS7 in open-access papers (continued):
Sharing a sentence is not in itself a finding about the gene and the disease.
cancer (18 papers, 2018 to 2026). A tumor composed of atypical neoplastic, often pleomorphic cells that invade other tissues. "Certain members, including DKC1, PUS1, and PUS7, have been implicated in oncogenic processes such as cancer stemness, metabolic reprogramming, and immune regulation across various malignancies." (PMID 41496500, 2026). "Dysregulation of PUS7 has been implicated in various pathological contexts, including various types of cancer, where it contributes to oncogenic processes such as cell proliferation, metastasis, metabolic reprogramming, and evasion of apoptosis." (PMID 40940790, 2025). "Additional work using in vivo models and patient-derived cancer cells will be necessary to explore the clinical implications of targeting PUS7 loss or aberrant tRNA fragment bioproduction in cancer." (PMID 33461542, 2021). "These insights not only underscore the importance of PUS7 in cancer biology but also pave the way for future investigations into the molecular mechanisms underpinning TNBC progression and the development of more effective, enzyme-targeted interventions." (PMID 41554761, 2026). "The Cancer Genome Atlas (TCGA) and Genotype-Tissue Expression (GTEx) database analysis clearly showed that PUS7 expression level is significantly increased by 26% in CRC tissue compared to normal tissue." (PMID 41168165, 2025). "This review summarizes the current understanding of PUS7 biology, its functional relevance in the contexts of cancer progression, and the growing interest in targeting RNA-modifying enzymes for therapeutic intervention." (PMID 40940790, 2025). "In pathological contexts such as cancer, PUS7 is frequently upregulated, likely reflecting its responsiveness to oncogenic signaling pathways." (PMID 40940790, 2025). "Integrating PUS7 targeting into rational combination therapies represents a compelling strategy to exploit cancer-specific vulnerabilities rooted in RNA regulation." (PMID 40940790, 2025). "PUS7 has emerged as a key regulator of cancer cell invasion and metastasis by modulating the post-transcriptional landscape of pro-metastatic genes." (PMID 40940790, 2025). "Emerging evidence suggests that aberrant PUS7 activity contributes to disease states such as cancer, where it promotes oncogenic pathways including MYC/MYCN signaling, metabolic reprogramming, and cell proliferation." (PMID 40940790, 2025). "Further validation in large, well-characterized cohorts is required to establish Ψ, particularly in relation to Ψ synthases like PUS7, as a robust, non-invasive cancer biomarker." (PMID 40940790, 2025). "Given the growing recognition of RNA-modifying enzymes as key regulators in cancer and other diseases, the development of selective, potent PUS7 inhibitors represents a promising therapeutic avenue." (PMID 40940790, 2025). "The therapeutic potential of targeting PUS7 lies in its emerging role as a regulator of RNA modifications that contribute to disease progression, particularly in cancers where they are aberrantly expressed or hyperactive." (PMID 40940790, 2025). "By catalyzing site-specific pseudouridylation on tRNAs, mRNAs, and non-coding RNAs, PUS7 regulates RNA stability, translation efficiency, and cellular stress responses, processes essential for sustaining rapid cancer cell growth." (PMID 40940790, 2025). "Inhibition or depletion of PUS7 sensitizes cancer cells to chemotherapy by impairing stress tolerance and promoting apoptosis, highlighting its potential as a target to overcome drug resistance." (PMID 40940790, 2025). "Collectively, these findings position PUS7 as a critical regulator of cancer cell homeostasis and a promising therapeutic target." (PMID 40940790, 2025). "PUS7 is one of the major mRNA pseudouridine synthase whose dysregulation leads to neurodevelopmental disorders and cancer, underscoring the critical function of PUS7-dependent pseudouridines." (PMID 41279304, 2025).
cancer (continued). "PUS7(Pseudouridine Synthase 7) is one of the pseudouridine synthases, but the literature on this enzyme is limited to several cancer types." (PMID 38819212, 2024). "To gain insights into the expression of PUS7 in different human cancer tissues, we first evaluated the PUS7 protein expression via the analysis of an independent human dataset (HPA024116) retrieved from the HPA database." (PMID 33990203, 2021). "Herein, ROC analysis aimed at discriminating cancer from normal tissue was performed to evaluate the sensitivity and specificity of PUS7 in GEO and TCGA data." (PMID 34827123, 2021). "Notably, elevated PUS7 expression consistently emerged as a significant adverse prognostic factor in multiple cancer types, strongly correlating with poorer clinical outcomes." (PMID 41496500, 2026). "Additionally, PUS7 has been identified as a potential biomarker for certain cancer types such as ovarian cancer." (PMID 41554761, 2026). "Moreover, gain-of-function studies demonstrate that PUS7 overexpression promotes cancer cell proliferation." (PMID 40940790, 2025). "Given PUS7’s role in supporting stress tolerance and translational reprogramming in cancer cells, its inhibition may render tumors more vulnerable to additional insults, such as DNA damage, oxidative stress, or nutrient deprivation." (PMID 40940790, 2025). "PUS7 plays a pivotal role in cellular stress adaptation and contributes to cancer progression." (PMID 40940790, 2025). "Emerging evidence suggests that PUS7 may modify distinct sets of tRNA and mRNAs in a cell type- and condition-specific manner, particularly in diseases such as cancer." (PMID 40940790, 2025). "The discovery of PUS7 inhibitors represents a significant step forward, offering new opportunities for targeted therapies aimed at correcting the dysregulation of pseudouridylation enzymes in cancer and potentially other diseases." (PMID 39834094, 2025). "For example, cancers with heightened dependence on the integrated stress response or aberrant RNA processing may exhibit synthetic lethality when PUS7 is suppressed." (PMID 40940790, 2025). "Of note, our pre-tests indicated that PUS7 is specifically highly expressed in CRC tissues and may promote CRC cells metastasis, supporting the hypothesis of a correlation between aberrant PUS7 expression and cancer development." (PMID 33990203, 2021). "Since transcription factors and signaling mediators such as ZEB1, SNAIL, E2F targets, and TGF-β effectors are known to orchestrate metastatic progression, it would be important to determine whether PUS7 regulates these effectors and contributes to cancer progression." (PMID 40940790, 2025). "It is unknown whether ALKBH3 can function as a substrate for PUS7 in other cancer types." (PMID 39175405, 2024). "PUS7, a stand-alone PUS, plays a critical role in promoting cancer cell proliferation and survival through its RNA-modifying activity." (PMID 40940790, 2025). "PUS7, PUS1, and DKC1 are significantly up-regulated in cancer tissue at both mRNA and protein levels." (PMID 37925171, 2023). "PUS7 was strongly stained in CRC tissues; in fact, its expression was more commonly observed in CRC tissues than in other cancer subtypes." (PMID 33990203, 2021). "NSCLC has not been studied for pseudouridine synthase 7 (PUS), a member of the PUS family that is associated with cancer development." (PMID 37420297, 2023). "NSCLC cell lines and tissues expressed high levels of PUS7, and PUS7 was found to influence the proliferation, migration, and invasion of cancer cells without affecting their apoptosis." (PMID 37420297, 2023). "Interestingly, cancer exosomes, but not normal exosomes, modulated expression of matrix remodelling (EFEMP1, DDK3, SPARC), cell cycle (EEF2K), membrane remodelling (LAMP2, SRPX), differentiation (SPRR2E), apoptosis (CTSC), transcription/translation (KLF6, PUS7)." (PMID 30008265, 2018).
hematological malignancies (2 papers, 2019 to 2025). "Furthermore, reduced expression of PUS7 has been implicated in hematological malignancies and clonal disorders." (PMID 31448224, 2019).
neurodevelopmental disorder (2 papers, 2025). A behavioral and cognitive disorder with onset during the developmental period that involves impaired or aberrant development of intellectual, motor, or social functions. "The generation of conditional or tissue-specific PUS7 knockout mouse models would enable detailed dissection of its roles in development, homeostasis, and disease progression, including tumorigenesis and neurodevelopmental disorders." (PMID 40940790, 2025).
PUS7 also shares sentences with these, for which no sentence is quoted: microcephaly (3 papers); Bladder Cancer (2); liver cancer (2); prostate carcinoma (2); sarcoma (2); thyroid cancer (2); triple-negative breast carcinoma (2); Adrenocortical Cancer (1); brain disorder (1); breast tumors (1); Digestive Diseases (1); hearing loss (1); hepatocellular carcinoma (1); Kidney (1); lung squamous cell carcinomas (1); mastitis (1); mesothelioma (1); prostate adenocarcinoma (1); renal cell carcinoma (1); uterine corpus endometrial carcinoma (1).